RPL8 (ribosomal protein L8)
Diseases named in the same sentence as RPL8 in open-access papers (continued):
Sharing a sentence is not in itself a finding about the gene and the disease.
cancer (12 papers, 2014 to 2025). A tumor composed of atypical neoplastic, often pleomorphic cells that invade other tissues. "We found that RPL8 can regulate transcriptome profiles, including gene expression and AS, which is highly associated with the pathogenesis and progression of cancers." (PMID 38155938, 2023). "By analyzing the functions of DEGs, we found that the DEGs by RPL8-OE were enriched in cancer-associated pathways, including inflammation, positive regulation of cell proliferation, angiogenesis, and innate immune response." (PMID 38155938, 2023). "Although the literature suggests that the two target genes (TP53BP1 and RPL8) and cancer development are associated, possible false positives may occur because the difference in temperature is too small." (PMID 40486861, 2025). "The results indicate that RPL8 could participate in the immune/inflammatory responses in cancer cells by regulating the expression levels of cancer-associated genes." (PMID 38155938, 2023). "In summary, this study provides profound insights into the possible functions of RPL8 in the development of cancers." (PMID 38155938, 2023). "This study reveals the important roles of RPL8 in regulating cancer cells at transcriptional and posttranscriptional levels, highlighting its potential value as a therapeutic target in cancer treatment." (PMID 38155938, 2023). "Consistent with our KEGG analysis, the downregulation of several genes that encode protein components of the ribosome (RPL8, RPS8, and RPL10A) in plasma is associated with cancer." (PMID 35816095, 2022). "Multivariate Cox regression showed that seven cancer-essential FRGs (ISCU, NFS1, MTOR, EIF2S1, HSPA5, AURKA, and RPL8) were significantly associated (p<0.05) with OS." (PMID 35756689, 2022). "After multivariate and LASSO analyses, seven cancer-essential FRGs (ISCU, NFS1, MTOR, EIF2S1, HSPA5, AURKA, and RPL8) were used to construct the risk model." (PMID 35756689, 2022). "We also found that the potential DEG targets of AS-TFs were enriched in the innate immune response and positive regulation of cell proliferation, suggesting that RPL8 may influence cancer-related DEGs by regulating the AS of these TFs." (PMID 38155938, 2023). "Therefore, RPL8 regulates cancer-related ASGs in HeLa cells." (PMID 38155938, 2023). "Furthermore, RPL8 may influence cancer-related DEGs by modulating the alternative splicing of transcription factors." (PMID 38155938, 2023). "The second analysis used CASC3 as the normalizing gene, and only identified two TaqMan assays (RPL8, TMBS10) that were classified as statistically significant, and they were both downregulated in cancer patients." (PMID 39146279, 2024). "Furthermore, RPL8 may influence cancer-related DEGs by modulating the splicing patterns of TFs." (PMID 38155938, 2023). "From these data, we selected potential biomarkers of cancer including six upregulated proteins (RNF213, CTSG, PGLYRP1, RPL8, S100A8, S100A9) and two downregulated proteins (GPX1, TNS1)." (PMID 34361002, 2021). "Other recurrent RPT expression patterns across cancer cohorts involved RPS4X, RPL13, RPL8 and RPL30." (PMID 29530001, 2018). "Interestingly, three proteins of the proteins found in this study (RNF213, RPL8, GPX1) were also discovered as differentially expressed in a study in which platelet mRNA of cancer patients was compared to that of healthy individuals." (PMID 34361002, 2021). "Six of these proteins had a higher abundance in cancer patients than in healthy controls (RNF213/ring finger protein 213; CTSG/cathepsin G; PGLYRP1/peptidoglycan recognition protein 1; RPL8/ribosomal protein L8; S100A8/S100 calcium binding protein A8; S100A9/S100 calcium binding protein A9)." (PMID 34361002, 2021).
infection (7 papers, 2011 to 2025). The state of being infected such as from the introduction of a foreign agent such as serum, vaccine, antigenic substance or organism. "Although the true receptor for RSV had not yet been identified, our results suggested that three ribosomal proteins (RPL5, RPL7a and RPL8) might play potential crucial roles in the infection and propagation of RSV in vector cells." (PMID 22028913, 2011). "We observed that under all the conditions tested (mock infection, 6 hpi, and 18 hpi), cytoplasmic ribosome proteins from the small (RPS6, RPS14, and RPS3) and large (RPL23a, RPL24, and RPL8) subunits were enriched in the ASFV-DP fraction." (PMID 29021398, 2017). "Previous studies comparing untreated HIV-infected individuals to healthy controls reported decreased expression of several ribosomal proteins, such as RPS27, RPL18A, RPL8, RPL26, RPL4, and RPS21, possibly reflecting impaired translational activity during active infection." (PMID 41226717, 2025).
RPL8 also shares sentences with these, for which no sentence is quoted: breast carcinoma (2 papers); head and neck carcinoma (2); brain cancer (1); COVID-19 (1); endocervical adenocarcinoma (1); hemorrhage (1); inflammatory bowel disease (1); ischemia (1); macrosomia (1); malaria (1); myeloma (1); serous ovarian cancer (1); T-cell lymphoma (1); viral infection (1).